ACOX1 (acyl-CoA oxidase 1)
Diseases named in the same sentence as ACOX1 in open-access papers (continued):
Sharing a sentence is not in itself a finding about the gene and the disease.
Mitchell syndrome (5 papers, 2023 to 2025). "In contrast, gain-of-function (GOF) missense mutations in ACOX1 (c.710A>G; p.N237S) result in Mitchell Syndrome (OMIM #618960), a rare neurodegenerative disorder characterised by sensorineural hearing loss, polyneuropathy, cognitive decline, and seizures." (PMID 39851575, 2025). "We developed a vertebrate (zebrafish) model of Mitchell syndrome using transient ubiquitous overexpression of the human ACOX1 N237S variant." (PMID 38357503, 2024). "Mitchell syndrome is a rare, neurodegenerative disease caused by an ACOX1 gain-of-function mutation (c.710A>G; p.N237S), with fewer than 20 reported cases." (PMID 38357503, 2024). "We developed a zebrafish model of Mitchell syndrome with ubiquitous overexpression of the human ACOX1 N237S variant." (PMID 38357503, 2024). "We developed a zebrafish model of Mitchell syndrome using transient ubiquitous overexpression of the human ACOX1 N237S variant tagged with GFP." (PMID 38357503, 2024). "Furthermore, excess of ROS in glia has been shown as the major contributor to the demyelination in patients with Mitchell syndrome caused by a gain of function mutation in the ACOX1 gene." (PMID 39958993, 2025). "Zebrafish Acox1 shares a 70% amino acid sequence identity to human ACOX1, including conservation of the asparagine 237 residue, which is critical for Mitchell Syndrome onset." (PMID 39851575, 2025). "Mitchell syndrome lacks a vertebrate model, limiting insights into the pathophysiology of ACOX1-driven white matter damage and neuroinflammatory insults." (PMID 38357503, 2024). "Mitchell syndrome currently lacks a vertebrate model, limiting insights into the role of ACOX1-driven white matter damage and neuroinflammatory insults." (PMID 38357503, 2024). "Unlike ACOX1 LOF mutations, Mitchell Syndrome does not result in elevated VLCFA levels." (PMID 39851575, 2025).
nonalcoholic fatty liver disease (5 papers, 2017 to 2024). "In mouse models of human nonalcoholic fatty liver disease (NAFLD), ACOX1 interacts with miR-222 and influences triglyceride formation in the cell." (PMID 39335247, 2024). "Emodin (0.25 or 0.5 μg/ml) was reported to attenuate nonalcoholic fatty liver disease (NAFLD) in zebrafish by activating AMPK pathway, via improving PI3K/AKT2/AMPKα-mediated IR and enhancing AMPKα/PPARα/CPT1 and AMPKα/PPARα/ACOX1-mediated fatty acid oxidation." (PMID 34629100, 2021).
oral squamous cell carcinoma (5 papers, 2022 to 2026). "Underexpression of ACOX1, observed in Oral Squamous Cell Carcinoma (OSCC) and linked to tumor growth inhibition, suggests its role in tumor suppression, supported by its association with tumor formation in breast and pancreatic cancers." (PMID 38594466, 2024). "The miR-31-5p-ACOX1 axis was shown to alter lipid metabolomes in oral squamous cell carcinoma." (PMID 35606603, 2022). "ACOX1 can be combined with MMP1, suppressor of cytokine signaling 3 (SOCS3) to diagnose oral squamous cell carcinoma (OSCC), and downregulation in bladder cancer might be due to PDK1 down-regulation, suggesting that it might serve as a potential biomarker and therapeutic target for bladder." (PMID 37724116, 2023).
dyslipidemia (4 papers, 2018 to 2025). "In the present study, chronic HFD feeding suppressed PPARα activation in the liver, which, in turn, downregulated lipolysis and fatty acid oxidation-related gene levels (LPL, CPT-1a, and ACOX1) and ultimately led to hepatic lipid deposition and dyslipidemia." (PMID 39942052, 2025). "ACOX1 was found to be increased by compounds including FGF19 (Fibroblast growth factor 19, a hormonal gut-derived peptide) and nordihydroguaiaretic acid (a Creosote bush metabolite), which have been shown to improve metabolic syndrome." (PMID 29765501, 2018).
liver fibrosis (4 papers, 2014 to 2025). "Inhibiting ACOX1 expression effectively improves steatohepatitis and liver fibrosis and inhibits the IL-1β and α-SMA pathways." (PMID 38595921, 2024). "In the present study, inhibition of ACOX1 by 10,12-tricosadiynoic acid improved steatohepatitis and liver fibrosis and significantly reduced liver inflammation and serum LDL levels." (PMID 38595921, 2024). "Furthermore, it should be emphasized that even in the presence of a large excess PUFA, peroxisome inhibition did not induce liver toxicity and was even protective confirming previous studies where liver‐specific ACOX1 KO reduced steatohepatitis and liver fibrosis through stimulation of lipophagy." (PMID 40726407, 2025). "However, inhibition of ACOX1 expression with 10,12-Tricosadiynoic acid in combination with middle- or low-dose OCA significantly improves steatohepatitis and liver fibrosis, with efficacy comparable to high-dose OCA, but without adverse effects on LDL and HDL levels." (PMID 38595921, 2024).
pseudoneonatal adrenoleukodystrophy (4 papers, 2020 to 2025). "Loss-of-function (LOF) mutations in ACOX1 cause a rare and severe autosomal recessive disorder known as peroxisomal acyl-CoA oxidase deficiency or pseudoneonatal adrenoleukodystrophy (P-NALD) (OMIM #264470), characterised by VLCFA accumulation." (PMID 39851575, 2025). "For example, pseudo neonatal adrenoleukodystrophy (P-NALD) is characterized by a deficiency in acyl-coenzyme A oxidase 1 (ACOX1)." (PMID 39765470, 2024). "Similarly, it has been observed that patients with pseudoneonatal adrenoleukodystrophy (a disease characterized by ACOX1 deficiency) show hepatomegaly due to impaired peroxisomal fatty acid β-oxidation of very long-chain fatty acids." (PMID 33114278, 2020).
renal fibrosis (4 papers, 2021 to 2023). A final common manifestation of a wide variety of chronic kidney diseases characterized by glomerulosclerosis and tubulointerstitial fibrosis. "Impaired PPARα and Acox1 activity have been implicated in age-associated renal fibrosis and can be reversed through calorie restriction." (PMID 35222262, 2021). "Suppression of the rate-limiting, PPARα-responsive peroxisomal enzyme, Acox1, has been described in experimental renal fibrosis and after treatment of tubular epithelial cells with TGF-β, a phenomenon reversed by the PPARα agonist fenofibrate." (PMID 35222262, 2021). "Decreased expression of Cpt1a and Acox1 prevents the mitochondrial oxidation of fatty acids, which further inhibits the availability of substrates and hinders fatty acid metabolism, and leads to renal fibrosis." (PMID 34987387, 2021).
Stroke (4 papers, 2018 to 2026). Sudden impairment of blood flow to a part of the brain due to occlusion or rupture of an artery to the brain. "Proteome-wide MR identified 242 proteins associated with BP, of which 48 were also linked to CAD or stroke, with four (ACOX1, FGF5, FURIN, MST1) also supported by genetic colocalization analyses (FDR 5% and PP ≥70%)." (PMID 41065563, 2026). "Genetically predicted FURIN and FGF5 were strongly associated with BP and stroke risk, while ACOX1, FGF5, and MST1 exhibited potential causal effects on CAD." (PMID 41065563, 2026). "Among these, genetically predicted levels of four proteins—ACOX1, FGF5, FURIN, and MST1—also demonstrated evidence of potential causal associations with CAD and/or stroke, supported by observational analysis." (PMID 41065563, 2026). "Of these, 5 proteins (ACOX1, BRAP, ERP29, FGF5, and FURIN) also showed strong colocalization with CAD and/or stroke and all had concordant direction of effects for BP and CAD and/or stroke." (PMID 41065563, 2026). "Using qRT‐PCR assays, we detected elevated mRNA expression of FA transporter CD36 and key mediators in FA β‐oxidation, including CPT1α, PPARα and ACOX1, confirming a hepatic shift towards enhanced FAO following stroke." (PMID 38666466, 2024).
Ataxia (3 papers, 2020 to 2024). Ataxia refers to impaired coordination of voluntary muscle movement. "This gene is of significant interest in human NAFLD lipid metabolism, as mutations in ACOX1 lead to elevated plasma concentrations of long straight-chain fatty acids in humans, accompanied by developmental delay, cerebellar ataxia, and language impairment." (PMID 39335247, 2024).
bladder cancer (3 papers, 2017 to 2025). "The bladder cancer data set showed that the expression of the ACOX1 gene was significantly associated with the expression of DAPK1." (PMID 41407823, 2025). "Further analysis of the 3 independent bladder cancer datasets have identified ACOX1, UPK2, TRAK1, PLEKHG6 and MT1X genes had their expression significantly correlated with that of DAPK1." (PMID 28388658, 2017). "Knockout of DAPK1 in the T24 cells of bladder cancer downregulated the expression of ACOX1." (PMID 41407823, 2025). "Knockdown of DAPK1 in bladder cancer T24 cells resulted in downregulation of ACOX1, UPK2 and TRAK1." (PMID 28388658, 2017).
liver disease (3 papers, 2018 to 2025). "This indicates a possible link between ACOX1 deficiency and liver disease progression, though exact causal mechanisms remain unclear." (PMID 40943222, 2025). "Targeting ACOX1 and ACOX2 could be considered a viable strategy for managing both liver disease and peroxisomal disorders." (PMID 40943222, 2025).
liver inflammation (3 papers, 2018 to 2024). "The set of genes that were down-regulated in tumor versus WT samples, and also in the tumor versus steatotic hepatitis samples, was enriched with lipid metabolic genes; the genes involved in fatty acid b-oxidation (e.g., Acaa1a, Acadvl, Acox1) were repressed." (PMID 30060537, 2018).
pancreatic cancer (3 papers, 2022 to 2025). "The expression of ACAA1 and ACOX1, target proteins of peroxisomal FAO, was significantly increased in pancreatic cancer tissue." (PMID 40848971, 2025). "To explore the impact of FAO activity in peroxisomes on pancreatic cancer, we compared the expression of ACAA1 and peroxisomal acyl-coenzyme A oxidase (ACOX1), the key proteins involved in FAO within peroxisomes, using commercially available pancreatic cancer tissue microarrays." (PMID 40848971, 2025).
psoriasis (3 papers, 2021 to 2022). An autoimmune condition characterized by red, well-delineated plaques with silvery scales that are usually on the extensor surfaces and scalp. "We have recently reported a key role of PPARδ signaling in the pathogenesis of AD and potentially of psoriasis, by up-regulating peroxisomal ß-oxidation via ACOX1, which contributes to shortening of SC lipid species, thereby initiating or perpetuating epidermal barrier impairment in AD." (PMID 35216234, 2022). "In lesional atopic dermatitis and psoriasis, the marked increase in ACOX1 might outstrip the detoxification ability of the cellular antioxidant response and contribute to the epidermal oxidative stress observed in both diseases." (PMID 34298981, 2021). "However, an enhanced PPARδ pathway induced by an impaired epidermal barrier might significantly contribute to ACOX1 upregulation in both ADL- and psoriasis-like inflammation." (PMID 34909730, 2021).
colon cancer (2 papers, 2023). "The results showed that the expression levels of ACSL6, CYP19A1, LRP2, OSBPL3 and SLCO1A2 were considerably increased, while those of ACOX1, FABP4, PLAAT5, PPARGC1A and TNFAIP8L3 were decreased in colon cancer." (PMID 38045683, 2023). "Hence, changes in ACOX content, localization and colocalization in peroxisome may be useful in preventing metabolic disorders or other ailments since recent studies suggested ACOX1 as a potential therapeutic biomarker in colon cancer." (PMID 37153362, 2023).
diabetic kidney disease (2 papers, 2022 to 2026). Progressive kidney disorder caused by vascular damage to the glomerular capillaries, in patients with diabetes mellitus. "Bailing Capsule activated the expression of PPARα, ACOX1 (acyl-CoA oxidase 1), and SCD (stearoyl-CoA desaturase) in diabetic nephropathy while suppressing the expression of FASN (fatty acid synthase)." (PMID 36091833, 2022).
glioma (2 papers, 2022 to 2024). A benign or malignant brain and spinal cord tumor that arises from glial cells (astrocytes, oligodendrocytes, ependymal cells). "Genes associated with inflammatory response (e.g., EIF2AK2, a key mediator of innate immunity) and fatty acid oxidation (e.g., acyl-CoA oxidase 1, the rate-limiting enzyme in fatty acid β-oxidation) were editing-regulated and associated with glioma progression." (PMID 35406793, 2022). "We showed that ACOX1 (acyl-CoA oxidase 1), the rate-limiting enzyme in fatty acid β-oxidation, was prognostic and editing-regulated in glioma." (PMID 35406793, 2022).
Hypertension (2 papers, 2010 to 2020). The presence of chronic increased pressure in the systemic arterial system. "The evidence resulting from this study suggests that PTGIS and ACOX1 are both potential causal torcetrapib off-targets, the inhibition of which may explain the side effect of hypertension." (PMID 20957118, 2010).
hypothyroidism (2 papers, 2021 to 2023). Abnormally low levels of thyroid hormone. "By contrast to a relatively homogeneous distribution present in euthyroid control, the majority of ACOX1-positive brown adipocytes were distributed within tissue in a Harlequin-like manner over the course of hypothyroidism (figure 2a5–a16), (figure 2a1, a2)." (PMID 37153362, 2023). "Blot analysis revealed an increased protein expression of ACOX1 on day 15 of hypothyroidism and it remained high until the end of treatment (day 21)." (PMID 37153362, 2023). "Namely, it was shown that hypothyroidism alters lipid metabolism in favour of long, branched fatty acids serving as an ACOX1 substrate." (PMID 37153362, 2023). "Single ACOX1-positive peroxisomes were predominantly present closely adjacent to LB with a linear increase in number over the course of hypothyroidism." (PMID 37153362, 2023). "On day 15 of hypothyroidism only single ACOX1-positive peroxisomes localized closely adjacent to the ER were present, while on other points of hypothyroidism, on days 7 and 21, we found both single ACOX1- and double ACOX1/ACOX3-positive peroxisomes." (PMID 37153362, 2023). "Herein, we demonstrated that hypothyroidism affects both ACOX1 and ACOX3 protein expression and induces their distinct tissue and cell heterogeneous localization/colocalization in BAT." (PMID 37153362, 2023). "In our study, the expression of Fasn, Acsl1, Acsl5, Ehhadh, and Acox1 were significantly down-regulated in hypothyroidism rats, indicating that the synthesis of fatty acid and the oxidation process of fatty acids were inhibited." (PMID 33959028, 2021). "Therefore, we used methimazole-induced hypothyroidism to study ACOX1 and ACOX3 protein expression and their tissue immunolocalization." (PMID 37153362, 2023). "Furthermore, in BAT, hypothyroidism acts in a similar way as cold exposure, inducing thermogenesis, i.e. increasing gene, immunoexpression and ACOX1 activity." (PMID 37153362, 2023). "This could have been a consequence of a transcription/translation switch that favours ACOX1 expression over the course of hypothyroidism." (PMID 37153362, 2023). "Previous studies showed that prolonged hypothyroidism in BAT can induce effects similar to cold exposure, resulting in increased ACOX1 activity, gene expression and immunoexpression in BAT." (PMID 37153362, 2023). "Most of the ACOX1 positive peroxisomes were single ACOX1-positive, although the number of double ACOX1/ACOX3-positive peroxisomes was substantial, and also increased in hypothyroidism." (PMID 37153362, 2023). "We further analysed ACOX1 and ACOX3 localization patterns and their colocalization within peroxisomes of single brown adipocytes over the course of hypothyroidism." (PMID 37153362, 2023). "These DEPs including Pygl, Pklr, Pc, Ehhadh, Acox1, Fasn, Acly, Acsl1, Acsl5, Pgm1, Suclg1, Gpt, Idh1, Fh, and Adh1 maight be as target proteins of AMR and its fractions for hypothyroidism." (PMID 33959028, 2021). "Like ACOX1, ACOX3-positive peroxisomes were predominantly adjacent to the LB and MTH and showed increase in number over the course of hypothyroidism, and this increase was biphasic with an exception of single ACOX3-positive peroxisomes closely adjacent to LB where increase was linear." (PMID 37153362, 2023). "Closely adjacent to the ER, ACOX3-positive peroxisomes showed exclusive pattern: absence on day 15, single ACOX3-positive peroxisomes presence on day 7, and double ACOX1/ACOX3-positive peroxisomes presence in euthyroid control and on days 7 and 21 of hypothyroidism." (PMID 37153362, 2023). "ACOX1 is the dominant isoform in BAT, that linearly increases over the course of hypothyroidism." (PMID 37153362, 2023). "The number of ACOX1-positive peroxisomes localized in cytoplasm was lower compared with peroxisomes closely adjacent to LB and MTH but showed the same biphasic increase over the course of hypothyroidism." (PMID 37153362, 2023).
hypothyroidism (continued). "A plausible explanation for the reduced ACOX3 expression in the early days of hypothyroidism may lay in the fact that hypothyroidism affects systemic lipid metabolism, which is reflected in the change of ACOX substrates for oxidation in BAT in favour of ACOX1." (PMID 37153362, 2023). "The number of single ACOX1-positive peroxisomes closely adjacent to MTH/LB was expectedly lower, and increase in number of ACOX1-positive peroxisomes (both single ACOX1 and double ACOX1/ACOX3-positive peroxisomes) was noticeable only on day 7 of hypothyroidism (figures 3b1, b2 and 4a)." (PMID 37153362, 2023).
lung carcinoma (2 papers, 2022). "Another study targeted gene associated with lung cancer and found four key genes that may affect lung cancer prognosis: MTIF2, ACOX1, CAV1, and MRPL17." (PMID 35039759, 2022).
lymphoma (2 papers, 2021 to 2022). A malignant (clonal) proliferation of B- lymphocytes or T- lymphocytes which involves the lymph nodes, bone marrow and/or extranodal sites. "In addition, ACOX1 destabilizes p73, thereby inhibiting the intrinsic apoptotic pathway of lymphoma cells and regulating the sensitivity to doxorubicin." (PMID 34124063, 2021). "Acyl-CoA oxidase 1 (ACOX1), a key rate-limiting enzyme in FAO, is overexpressed in malignant lymphomas and confers resistance to the anthracycline antibiotic doxorubicin, mainly by reducing doxorubicin-induced activation of caspase-9 and caspase-3 and reduction of mitochondrial membrane potential." (PMID 36106108, 2022).
prostate carcinoma (2 papers, 2020 to 2025). A carcinoma that arises from epithelial cells of the prostate gland. "Higher expression levels of ACOX1 were detected in PC3 cells, a cell line with prostatic small cell carcinoma, compared to 22RV1 cells (a human prostate carcinoma epithelial cell line)." (PMID 40565311, 2025).
type 2 diabetic (2 papers, 2012 to 2015). "In our results, although the mRNA expression of PPARα had no changes, the enhanced mRNA expressions of ACOX1, 3 and mCPT-1 (PPARα targets) represented the activation of PPARα in the type 2 diabetic rat heart." (PMID 23057715, 2012).
alcoholic liver diseases (1 paper, 2024). A disorder caused by damage to the liver parenchyma due to alcohol consumption. "Evidence in a mouse model of alcoholic liver disease demonstrated that PtdCho administration significantly reduced ethanol-induced ACOX1 activity." (PMID 38664334, 2024).
astrocytoma (1 paper, 2020). "This study revealed a distinct mechanism by which EV71 induces apoptosis and autophagy through attenuation of ACOX1 production and promotion of ROS generation in neuroblastoma and astrocytoma cells." (PMID 32434419, 2020). "In addition, endogenous ACOX1 protein level was also down-regulated upon EV71 infection in dose-dependent manners in both human neuroblastoma (SK-N-SH) cells and human astrocytoma (U251) cells." (PMID 32434419, 2020). "Additionally, knockdown of ACOX1 or peroxin 19 (PEX19) induces apoptosis and autophagy in neural cells including human neuroblastoma (SK-N-SH) cells and human astrocytoma (U251) cells, and EV71 infection induces neural cell death through attenuating ACOX1 production." (PMID 32434419, 2020).